IL1B (interleukin 1 beta)
Diseases named in the same sentence as IL1B in open-access papers (continued):
Sharing a sentence is not in itself a finding about the gene and the disease.
glaucoma (61 papers, 2007 to 2026). Increased pressure in the eyeball due to obstruction of the outflow of aqueous humor. "IL-1β is reported to be increased in the blood of glaucoma patients, causing neurotoxic inflammation that leads to axonal degeneration and retinal RGC death." (PMID 40722741, 2025). "On the other hand, 5-HT4R activation reduces astrocyte responses and inflammatory mediators such as IL-1β, and chronic inflammation is an important causative factor of optic nerve damage in glaucoma." (PMID 41041445, 2025). "Interleukin-1β levels have also been shown to increase in the aqueous humour of patients with glaucoma, and single-nucleotide polymorphisms in the IL-1β gene have been associated with a risk of glaucoma." (PMID 41226385, 2025). "Remarkably increased gene and protein levels of IL-1β were found in the blood and aqueous humor of glaucoma patients, establishing IL-1β as a risk factor in glaucoma pathogenesis." (PMID 35576057, 2022). "Several studies have suggested that BAK increases the levels of cytokines such as IL-6, IL-8 and IL-1β in the tears of patients using glaucoma eyedrops and that these inflammatory regulators cause ocular discomfort." (PMID 33271908, 2020). "In glaucoma, microglial activation and an inflammatory response involving Toll-like receptors (TLRs), complement molecules and cytokines, such as TNFα and IL-1β, is associated with secondary phase of the disease." (PMID 25301432, 2014). "It has been reported that polymorphisms in the IL1A and IL1B genes are associated with Primary Open Angle Glaucoma (POAG)." (PMID 20565898, 2010). "In rodent models of glaucoma, IL-1β is demonstrated to cause an increase in RGC death, hypothesized to be activated via a TLR4-NLRP1/NLRP3-CASP8-axis in an acute IOP glaucoma model in mice." (PMID 31379825, 2019). "IL-1β is upregulated prior to axon degeneration or RGC loss in the D2 model of glaucoma." (PMID 30424795, 2018). "Overactivation of microglia can result in the production of proinflammatory cytokines, including interleukin (IL)-1β, and promote the progression of glaucoma." (PMID 40722741, 2025). "Activation of NF-κB, a key regulator of inflammation, is typically associated with the expression of proinflammatory cytokines, such as TNF-α and IL-1β, which exacerbate neuronal damage in glaucoma." (PMID 40970091, 2025). "A considerable interest exists in the role of IL-1β in glaucoma, including a consideration of targeting IL-1β production as a therapeutic strategy." (PMID 41226385, 2025). "Inflammatory factors, such as TNF, IL-1β, IL-18 and MMP, can promote the death of RGCs, which is a hallmark of glaucoma development." (PMID 38437213, 2024). "According to our meta-analysis findings, resveratrol demonstrates the ability to diminish inflammatory cytokines like iNOS, COX-2, IL-6, and IL-1β in a model of glaucoma-related retinal injury." (PMID 39881870, 2024). "Combined, these data indicated that RGCs and astrocytes are the two key types of inner retinal cells contributing to IL-1β release into the vitreous fluid during the progression of OHT-induced glaucoma." (PMID 37998361, 2023). "In a glaucoma mouse model, increased expressions of inflammatory cytokines, including interferon-γ, IL-6, IL-4, IL-10, and IL-1β were found." (PMID 37744880, 2023). "Proinflammatory microglia/macrophages and neurotoxic astrocytes were the main source of proinflammatory cytokines such as TNF and IL-1β in the context of glaucoma." (PMID 35132339, 2022). "In the present study, we detected the formation of proinflammatory microglia/macrophages and neurotoxic astrocytes, deposition of complement C3, and production of proinflammatory cytokines (TNF and IL-1β) in the rat glaucoma model we previously used." (PMID 35132339, 2022). "In this regard, lactate-mediated HCA1R activation was shown to reduce various inflammatory markers, such as NLRP3 and interleukin (IL)-1β, in a mouse model of glaucoma." (PMID 35805182, 2022).
glaucoma (continued). "In studies focusing on prostaglandin analogue-treated glaucoma patients, IL1B, IL6, and matrix metallopeptidases 1, 3, and 9 (MMP1, MMP3, and MMP9) were seen to be increased, while TIMP metallopeptidase inhibitors 1 and 2 (TIMP1 and TIMP2) were decreased." (PMID 35897711, 2022). "Based on these studies, we consider that NLRP3-dependent IL-1β plays a crucial role in inflammation and RGCs death in the glutamate-induced glaucoma model, while the exact pathway by which it triggers inflammation is worthy of further investigation." (PMID 36289519, 2022). "Clinical studies have observed an upregulation level of IL-1β mRNA and protein expression in the blood of glaucoma patients, suggesting activation of the NLRP3 inflammasome in glaucoma." (PMID 34925047, 2021). "Immune inflammatory response mediators like proteolytic enzymes and pro-inflammatory cytokines (TNF-α, IL-1β, IL-6, IL-12, and NO) have recently become a target of glaucoma research." (PMID 33803434, 2021). "An increase in inflammatory cytokines IFN-γ, IL-6, IL-4, IL-10, and IL-1β resulted in a reduction of brn3a+ RGC cells in a glaucoma mouse model, and is thought to be related to microglial activation." (PMID 34439904, 2021). "We found a nominally significant association of GSTM1 gene deletion with decreased risk of ocular hypertension and a protective role of IL1B rs16944 and IL6 rs1800629 in the risk of glaucoma." (PMID 33803434, 2021). "Presently, TDRD7, CYP1B1, GJA1, IL1B, MMP1, and MMP3 have been considered as a causative gene for glaucoma." (PMID 33299458, 2020). "The mechanism by which P2X7-mediated IL-1β secretion occurs in glaucoma has been suggested by this group and others to occur in response to stretch and swell mechanical stresses from increased IOP." (PMID 31379825, 2019). "As shown in the analysis, there is a major association with Th1-cytokines in the case of glaucoma only (IL2, IL12), and a minor association with keratitis (IL2) and scleritis (IL1β)." (PMID 31810226, 2019). "We also observed comparable trends for pro-inflammatory regulations in glaucomatous retinal tissues in our study like elevated concentrations of TNF-α (p = 0.13), IL-1β (p = 0.08), IL-6 (p = 0.26) and IL-8 (p = 0.04) compared to non-glaucoma controls." (PMID 23451242, 2013). "Interestingly, IL-1β and inflammasome activation have been described in RGCs and retinal astrocytes in association with RGC loss in glaucoma models, demonstrating a link between innate immunity and neurodegeneration." (PMID 39875919, 2025). "It is known that the inflammatory pathological milieu consequent to both glaucoma surgery wound and topical long-term glaucoma treatment further induces conjunctival fibroblasts to secrete various growth factors and proinflammatory cytokines, such as IL-1β and IL-6." (PMID 38391973, 2024). "It was found that Ba alleviates the expression of pro-inflammatory cytokines including TNF-α, IL-6, and IL-1β in mouse microglia, supporting its biomedical significance for glaucoma treatment as elevated levels of TNF-α, IL-6, and IL-1β are observed in the TM of glaucoma patients." (PMID 35806375, 2022). "While IL1B and IL6 may be associated with the risk of glaucoma, GPX and TNF may affect the glaucoma phenotype." (PMID 33803434, 2021). "The increased inflammatory cytokines IL-1β, IL-4, IL-6, IL-10, and IFN-γ, in turn, led to a reduction in RGCs in the glaucoma model, which might be associated with microglial activation." (PMID 34925047, 2021). "Accordingly, treatments targeting macrophage-derived pro-inflammatory cytokines, such as IL-1β, may be used in the future treatment of glaucoma." (PMID 33796062, 2021). "In conclusion, genetic variability in IL1B and IL6 may be associated with glaucoma risk, while GPX and TNF may be associated with the glaucoma phenotype." (PMID 33803434, 2021).
glaucoma (continued). "The anti-inflammatory properties of iTRAB® were investigated in 3D-HTMCs through its ability to modulate the increase in pro-inflammatory (i.e., IL-1α, IL-1β, IL-6, and TNF-α) and pro-fibrotic cytokines, as well as MMPs which are known to be associated with glaucoma." (PMID 33172106, 2020). "We then examined the gene expression of several proinflammatory cytokines (TNFα, IL-1β, IL-6, and IL-18) and chemokines (MIP-1α, MIP-1β, MIP-2, MCPI, and IP10) that have been implicated in human and experimental models of glaucoma." (PMID 31570110, 2019). "IL-1β expression was also reduced specifically in IL-6−/− retina with microbead-induced glaucoma." (PMID 27747134, 2016). "Likewise, an increased production of TNF and IL-1β has been observed in glaucomatous animal models and in human glaucoma." (PMID 26054642, 2015). "An increased protein level was measureable for TNF-α (TNF-α: ctrl = 538±200 U, glaucoma = 907±454 U; p = 0.13) and the interleukins IL-1ß (IL-1β: ctrl = 11262±2590 U, glaucoma = 15625±4194 U; p = 0.08) and IL-6 (IL-6: ctrl = 8301±2287 U, glaucoma = 12073±6695 U; p = 0.26)." (PMID 23451242, 2013). "Moreover, on the molecular level, LUT-EX@MN arrays reversed glaucoma-induced biochemical changes, such as the inflammatory markers; TNF-α, IL-8, and IL-1β, glaucoma-related biomarkers; MYOC, NRF2, and TIMP1 and the activity of glutathione peroxidase to levels comparable to healthy controls." (PMID 40643885, 2026). "However, we did detect increases in IL-1α and IL-1β, which are also elevated in glaucoma." (PMID 31354422, 2019). "The integrated system significantly reversed glaucoma-induced changes in TNF-α, IL-8, MYOC, NRF2, TIMP1, and IL-1β levels, resembling those of the healthy group." (PMID 40643885, 2026). "In the present study, we used an ex vivo rat glaucoma model to investigate the microglial signaling pathway mediating RGC death and describe key roles of TLR4 and IL-1β." (PMID 40722741, 2025). "Inflammatory cytokines, such as TNF-α, IL-1β and IL-6, have been identified to clearly contribute to RGC death in glaucoma." (PMID 40528237, 2025). "The onset of the inflammatory process in glaucoma is triggered by impaired communication between RGCs and glial cells, inducing the release of proinflammatory mediators, such as ROS, NO, TNF-α, and IL-1β." (PMID 38333055, 2024). "Most likely other inflammatory cytokines are involved as well, especially IL-6 and IL-1β, but the role of TNF-α in glaucoma has been under strong suspicion for over two decades." (PMID 37803488, 2024). "Previous studies have shown that increased mRNA and protein levels of IL-1β, a signal of NLRP3 inflammasome activation, were observed in the blood of glaucoma patients." (PMID 36289519, 2022). "Caffeine, an unspecific A2AR antagonist, was neuroprotective, as it lowered intraocular pressure and reduced the activation of microglia and the inflammatory cytokines IL-1β and TNF-α in a mouse glaucoma model." (PMID 35387355, 2022). "Inhibition of HMGB1 resulted in reduced NLRP3 and IL-1B levels, which also reduced RGC death and glaucoma severity." (PMID 34439904, 2021). "The current study provides novel insights that pro-inflammatory cytokines such as IL-1β and IL-6 are regulated by δ-opioids via STAT3-dependent pathways in rat glaucoma model." (PMID 33628191, 2021). "Clear trends exist between the role of IL-1β as a regulator of cytokine production and cell death across many retinal diseases including AMD, DR, RP, glaucoma and ROP, and IL-18, which modulates neovascular aspects of these diseases." (PMID 31379825, 2019).
glaucoma (continued). "Many of the cytokines with increased expression measurements in our study (IL-1α, IL-1β, IL-6, TNF-α, FasL) were already described as being elevated in glaucoma patients." (PMID 30967499, 2019). "However, in prolonged glaucoma pathology, uncontrolled microglial activation leads to the release of neurotoxic pro-inflammatory cytokines, including TNF-α, IL-6, and IL-1β, exacerbating neurodegeneration." (PMID 40457155, 2025). "Previous studies also suggest that during glaucoma macrophages produce cytokines such as IL6, IL1β and TNFα that could lead to an acute inflammatory response." (PMID 35619185, 2022). "Several cellular junction proteins maintain the BRB, and during bacterial infection and other ocular inflammation models (e.g., uveitis and glaucoma), increased inflammatory mediators (e.g., IL-6, MIP2, TNF-α, and IL-1β) can impair the barrier properties (24, 62, –, 66)." (PMID 35913202, 2022). "In our experimental glaucoma model, molecules released by reactive macroglia such as TNF-α and IL-1β could induce the secondary death of RGCs." (PMID 35625676, 2022). "Additionally, a glaucoma animal model, DBA2J, developed PAS and iris atrophy with age, and the AqH levels of IL-1β, IL-6, IL-10, IFN-γ, TNF-α, MCP-1 and GM-CSF at 50 weeks were significantly higher than those at 8 weeks." (PMID 34830147, 2021). "Increased levels of IL-1β mRNA and protein have also been observed in the blood of glaucoma patients compared with controls, suggesting activation of the NLRP3 inflammasome in glaucoma." (PMID 34439904, 2021). "IL-1β was significantly elevated in both proximal and distal portions of the optic nerve in DBA/2J mice compared to controls, indicating a possible role for this cytokine in distal axonopathy in glaucoma." (PMID 33669765, 2021). "In rodent glaucoma models, where mice were exposed to either hypoxic damage or ocular hypertension, a release of TNF-α and IL-1β from activated microglia accompanied by apoptosis of RGCs was found, supporting the involvement of microglia in glaucomatous neurodegeneration." (PMID 33796062, 2021). "Il-1α and Il-1β mRNAs were found to be increased in the TM in glaucomatous eyes compared to controls, acting in a feedback loop to control endothelial leukocyte adhesion molecule 1 (ELAM-1), an early marker of atherosclerotic plaque that forms in glaucoma." (PMID 31379825, 2019). "In glaucoma, IL-1β was found to be one of the first inflammatory cytokines upregulated in the ONH, and is a powerful stimulus for immune cell recruitment, further supporting the role of neurotoxic inflammation as a significant contributor to the neurodegenerative process of glaucoma." (PMID 34439904, 2021). "Notably, IL-1β was significantly elevated in both proximal and distal portions of the optic nerve in DBA/2J mice compared to controls, indicating a possible role for this cytokine in distal axonopathy in glaucoma." (PMID 26376776, 2015). "In conclusion, reduction in IL-6 would help in reducing the effects of glaucoma as with the other inflammatory cytokines of CXCR4, IL-17, IL-1β, and TNF-α which are known to be increased in PC-12-glaucoma model cells without betalain treatment." (PMID 32666339, 2020). "GM-CSF, IFN-γ, IL-1β, and TNF-β were detected in less than 50 % of samples in both control and glaucoma groups and therefore were not included in further analysis." (PMID 26748993, 2016).
myocardial ischemia (61 papers, 2007 to 2026). A disorder of cardiac function caused by insufficient blood flow to the muscle tissue of the heart. "The significant negative correlation between IL-1β expression and CFR suggests that the inflammatory milieu driven by IL-1β impairs the function of the coronary microvasculature, leading to myocardial ischemia and contributing to the heightened risk of MACE." (PMID 41573504, 2025). "The effect of sevoflurane on myocardial ischemia has been shown in both in vivo and in vitro models, and is associated with anti-inflammation and the inhibition of inflammasomes, IL-1β, IL-18, and cell pyroptosis." (PMID 39202513, 2024). "Further studies showed that the stimulus of cardiac ischemia/reperfusion caused a remarkable increase in the expression levels of interleukin-1β (IL-1β), IL-6, and tumor necrosis factor-α (TNF-α) mRNA in ischemic heart tissue, which was effectively prevented by pretreatment with SIN." (PMID 35837272, 2022). "The compound effectively inhibited TNF-α, IL-1β, and IL-6 levels in myocardial ischemia–reperfusion models while suppressing necroptosis through transforming growth factor-beta-activated kinase 1 (TAK1) phosphorylation regulation." (PMID 41155644, 2025). "In myocardial ischemia/reperfusion models, Rg2 treatment significantly inhibited the expression of TNFα, IL-1β, IL-6, and monocyte chemoattractant protein-1 (MCP-1)." (PMID 41155644, 2025). "Here, we focus on IL1β-modeled chronic inflammation, as targeting IL1β signaling is a promising cancer therapeutic target and improves outcomes of cardiac ischemia in murine models of CH15." (PMID 38062031, 2023). "In contrast, the expression of IL-1β quickly increases after the acute phase of myocardial ischemia and its inhibition is detrimental, delaying scar formation and promoting cardiac rupture." (PMID 35406729, 2022). "A recent study demonstrated that anti-inflammatory therapy targeting IL-1β suppression decreased cardiovascular events in myocardial ischemia patients." (PMID 33796569, 2021). "Myocardial ischemia is a potent stimulus that causes the activation of MCs in the heart and the release of cytotoxic mediators such as IL-6, TNF-α, and IL-1β." (PMID 34512339, 2021). "M1 macrophages expressed TNF-α, iNOS, IL-1β, and IL-6, which induced a strong proinflammatory reaction and contributed to myocardial ischemia-reperfusion injury." (PMID 34094602, 2021). "It is known that SIRT1 can inhibit the expression levels of p65, TNF-α, IL-1β, IL-6, iNOS, and other markers related to oxidative stress by regulating the NF-κB pathway, thus playing a role in myocardial ischemia-reperfusion." (PMID 34868528, 2021). "The release of PCSK9 during cardiac ischemia results in cell death and dysfunction; inflammatory stimuli (i.e., IL-1β) are considered to be powerful inducers for PCSK9 secretion in both macrophages and tissues such as heart and aorta." (PMID 34576046, 2021). "The release of inflammatory factors, such as TNF-α, IL-1β, and others, have been found to play important roles in mediating and exacerbating myocardial ischemia/reperfusion injury." (PMID 32116705, 2020). "The levels of LDH, IL-1β and NO were markedly increased (P < 0.001), indicating obvious myocardial injury after the myocardial ischemia–reperfusion." (PMID 32210797, 2020). "Another report showed the reduced release of TNF-α, IL-1β, and IL-6 in myocardial ischemia/reperfusion (MI/R) rats treated with MLB." (PMID 33014451, 2020). "Myocardial ischemia/reperfusion can cause an increase in the levels of cytokines such as TNF-α, IL-6, and IL-1β." (PMID 30944548, 2019). "IL-1β and IL-18 both belong to the IL-1 superfamily and recent evidence shows that IL-1β activates IL-18 in the course of myocardial ischemia/reperfusion injury and acute heart failure." (PMID 31247004, 2019). "The elevation of cardiac markers (such as LDH, cTn) and inflammatory cytokines (such as IL-1β) are important bases for the diagnosis of myocardial ischemia injury." (PMID 31816891, 2019).